ARHGDIA (Rho GDP dissociation inhibitor alpha)
Diseases named in the same sentence as ARHGDIA in open-access papers:
ARHGDIA is named in the same sentence as 81 diseases in open-access papers, as found by Europe PMC text mining. Sharing a sentence is not in itself a finding about the gene and the disease. The quoted sentences say what the papers report.
breast carcinoma (16 papers, 2006 to 2024). "Loss of ARHGDIA enhances metastasis and resistance to tamoxifen in breast cancer and promotes the development and progression of prostate cancer." (PMID 26761212, 2016). "Loss of ARHGDIA enhances metastasis and resistance to tamoxifen in breast cancer and loss of ARHGDIA expression promotes the development and progression of PCa." (PMID 22928040, 2012). "However, a significant reduction of ARHGDIA expression is detected in breast cancer." (PMID 27726098, 2016).
hepatocellular carcinoma (10 papers, 2013 to 2024). A malignant tumor that arises from hepatocytes. "This miRNA has previously been linked to gain and subsequent up-regulation causing cell migration and invasion in hepatocellular carcinoma by targeting Rho GDP dissociation inhibitor alpha (RhoGDIA), which is a putative metastasis suppressor." (PMID 24257477, 2013). "In addition, ARHGDIA downregulation is associated with poor prognosis in hepatocellular carcinoma." (PMID 27726098, 2016). "Upregulation of miR-25 can inhibit the Rho GDP dissociation inhibitor alpha (RhoGDI1), enhancing expression of Snail and exerting its pro-metastatic function in hepatocellular carcinoma." (PMID 27992370, 2017). "In contrast, ARHGDIA expression is reduced in brain cancers and hepatocellular carcinoma." (PMID 26761212, 2016). "A recent article has reported that ARHGDIA is decreased in hepatocellular carcinoma, and its expression is regulated in part by the recently characterized miR-151-5p, which is located in an intron of the gene encoding focal adhesion kinase (FAK) and is expressed with FAK." (PMID 26761212, 2016).
glioblastoma (6 papers, 2016 to 2024). The most malignant astrocytic tumor (WHO grade IV). "Moreover, ARHGDIA expression differs in different histological gliomas, including pilocytic astrocytoma, diffuse astrocytoma, anaplastic astrocytoma, and glioblastoma." (PMID 27726098, 2016).
prostate carcinoma (6 papers, 2017 to 2024). A carcinoma that arises from epithelial cells of the prostate gland. "METTL3 stabilizes ARHGDIA mRNA by modulating ELAVL1 expression in prostate cancer." (PMID 36348434, 2022).
glioma (5 papers, 2011 to 2019). A benign or malignant brain and spinal cord tumor that arises from glial cells (astrocytes, oligodendrocytes, ependymal cells). "Our analyses reveal that ARHGDIA is frequently downregulated in human glioma tissues and it is significantly associated with tumor malignancy degree." (PMID 27726098, 2016). "Generally, ARHGDIA expression level is associated with tumor grade, survival, and prognosis of glioma patients." (PMID 27726098, 2016). "ARHGDIA, encoding a Rho GDP-dissociation inhibitor, is implicated in cell migration and is upregulated in several cancers including glioma." (PMID 29880060, 2018). "Together, our analyses show that the protein level of ARHGDIA, which is known to be a negative regulator of Rho GTPases such as Rac1, Cdc42 and Rho, is decreased in glioma tumors compared with control brain tissues." (PMID 26761212, 2016). "Next, cell migration was further analyzed to know if ARHGDIA has a crucial role in glioma cell migration ability." (PMID 27726098, 2016). "Due to the important role of ARHGDIA in the regulation of Rho GTPase, then how does its decreased expression regulate its effector proteins including Rac1/cdc42 and RhoA in glioma cells?" (PMID 27726098, 2016). "As the regulator of Rho GTPases family, we further focus on the changes of Rho GTPase proteins after ARHGDIA knockdown in human glioma cells." (PMID 27726098, 2016). "Our research showed that ARHGDIA is frequently down-regulated in human glioma and significantly correlates with prognosis of glioma patients." (PMID 27726098, 2016). "The results demonstrated that overexpression of ARHGDIA dramatically inhibits both migration and invasion of the glioma cells." (PMID 26761212, 2016). "In our previous work, we have demonstrated that ARHGDIA is a target mRNA of the RNA-binding protein PCBP2 in gliomas, on the basis of RIP-Chip data and biotin pull-down assays." (PMID 26761212, 2016). "By now, we found that knockdown of ARHGDIA by siRNA resulted in activating the GTPase activity of Cdc42, Rac1, RhoA, and pAkt to promote glioma cell proliferation and migration." (PMID 27726098, 2016). "The results suggest that ARHGDIA downregulation promotes glioma cell proliferation by regulating cell cycle distribution." (PMID 27726098, 2016). "The expression levels of ARHGDIA in glioma exhibit a tumor pathological grade-dependent pattern (p = 0.048)." (PMID 27726098, 2016). "We sought to elucidate the interaction between PCBP2 and miR-151-5p/miR-16 in promoting the motility and invasiveness of glioma cells through downregulating ARHGDIA." (PMID 26761212, 2016). "These different expression profiling even opposite results on this protein in several cancers urgently drives us to know how ARHGDIA mediates the processes during tumorigenesis and cancer progression in human glioma." (PMID 27726098, 2016). "The rescue study suggested that PCBP2 influences glioma migration and invasion directly through ARHGDIA." (PMID 26761212, 2016). "In the present study, we further investigated the role of ARHGDIA in human glioma, and we firstly discovered the relationship between the dysregulation of ARHGDIA and glioma progression." (PMID 27726098, 2016). "So based on the results of our research and literature reported, the potential action mechanism of ARHGDIA in glioma is summarized as following." (PMID 27726098, 2016). "Strong expression of the ARHGDIA protein but not mRNA was found in the 6 control brain tissues, but there was a clear loss of ARHGDIA in grade III and grade IV glioma tissues." (PMID 26761212, 2016). "Compared with the expression level in PBTs, ARHGDIA was greatly decreased in glioma tissues both at mRNA and protein levels." (PMID 27726098, 2016). "This indicated that the migration potential of human glioma cells was markedly promoted after knockdown of ARHGDIA." (PMID 27726098, 2016).
glioma (continued). "In this study, we discovered that ARHGDIA is much downregulated in human glioma; meanwhile, its expression negatively correlates with glioma malignancy and positively relates to prognosis of glioma patients." (PMID 27726098, 2016). "In order to evaluate whether ARHGDIA is a potential diagnosis or prognosis factor in clinical test, we analyzed the relationship between the expression of ARHGDIA and the clinicopathologic features of human glioma patients." (PMID 27726098, 2016). "So our investigation aim is to explore ARHGDIA functions in glioma development." (PMID 27726098, 2016). "ARHGDIA is a potential prognostic marker and therapeutic target for human glioma." (PMID 27726098, 2016). "However, in addition to the functional verification of ARHGDIA, we notably uncovered the relationship between miRNAs and RBPs in modulating the expression and function of a common target gene in glioma migration and invasion." (PMID 26761212, 2016). "Furthermore, we demonstrated that ARHGDIA is a potential target of miR-151-5p and miR-16 in gliomas." (PMID 26761212, 2016). "To investigate the biological function of ARHGDIA in gliomas, we constructed a recombinant adenovirus encoding a green fluorescent (GFP) fusion protein—GFP-ARHGDIA protein (AD-ARHGDIA, 55 kDa)—and used the recombinant adenovirus encoding GFP protein (AD-GFP, 28 kDa) as a negative control." (PMID 26761212, 2016). "PCBP2 may facilitate miR-151-5p and miR-16 promotion of glioma cell migration and invasion through mitigating the function of ARHGDIA." (PMID 26761212, 2016). "After the adenoviral transduction for 48 to 72 hours in 4 glioma cell lines (T98G, U87 MG, A172 and U251), western blotting analysis confirmed that a high level of ARHGDIA protein expression was achieved in infected cells compared with the negative control-infected cells." (PMID 26761212, 2016). "In conclusion, the ARHGDIA downregulation may be an important contributor to cell migration, and the expression level of ARHGDIA affects the metastatic behavior of human glioma cell lines." (PMID 27726098, 2016). "Previous studies have indicated the aberrant expression of ARHGDIA is associated with cancers, whereas there is no research in detail on glioma." (PMID 27726098, 2016). "We demonstrated that ARHGDIA is a potential target of miR-151-5p and miR-16 in gliomas." (PMID 26761212, 2016). "Therefore, the downregulation of ARHGDIA regulates GTPase activity of Cdc42, Rac1, and RhoA, subsequently, increases Akt phosphorylation and leads to glioma cell proliferation and migration." (PMID 27726098, 2016). "To evaluate whether overexpression of ARHGDIA inhibited EMT-related changes, we first assessed the EMT-related genes after infection with AD-GFP and AD-ARHGDIA using western blotting analysis in the T98G cell line, which is the most commonly used cell line in glioma research." (PMID 26761212, 2016). "However, it remains elusive whether and how ARHGDIA plays functions in human glioma." (PMID 27726098, 2016). "Collectively, these data suggest that ARHGDIA is an enforcer of the epithelial phenotype and an inhibitor of EMT in gliomas." (PMID 26761212, 2016). "Consistently with the results of the overexpression of ARHGDIA, knockdown of PCBP2 also reversed the mesenchymal-like characteristics of glioma cells." (PMID 26761212, 2016). "Additionally, we also measured mRNA and protein levels of ARHGDIA in 4 normal human astrocyte cell lines (HA, NHA, HA-c and HA-sp), 1 human embryonic brain cell line (HEB) and 4 different human glioma cell lines (T98G, U87 MG, A172 and U251)." (PMID 26761212, 2016). "Generally, a lower expression of ARHGDIA widely exists in gliomas than that in noncancerous brain tissues (p < 0.05)." (PMID 27726098, 2016). "As results, more than one thirds of human glioma tissues (n = 25, 34.2 %) had ARHGDIA-negative expression, and other 48 cases (65.8 %, 48/73) showed weak expression of ARHGDIA in cytoplasm, with mean staining scores 1.396 ± 0.08." (PMID 27726098, 2016).
glioma (continued). "The results showed that the protein level but not mRNA expression of ARHGDIA was frequently downregulated in glioma tissues compared with control brain tissues." (PMID 26761212, 2016). "Then, we transfected AD-GFP and AD-ARHGDIA into epithelial-like HeLa cells and T98G cells and observed that overexpression of ARHGDIA inhibited EMT-like morphological features, such as a spindle-shaped appearance of HeLa cells, and reversed the mesenchymal-like characteristics of glioma cells." (PMID 26761212, 2016).
lung adenocarcinoma (3 papers, 2015 to 2017). A carcinoma that arises from the lung and is characterized by the presence of malignant glandular epithelial cells. "miR-483-5p but not miR-483-3p was recently shown to induce epithelial to mesenchymal transition (EMT) and to promote lung adenocarcinoma cell migration in vitro by targeting Rho GDP dissociation inhibitor alpha (RhoGDI1) and activated leukocyte cell adhesion molecule (ALCAM)." (PMID 26834703, 2015).
malignant glioma (3 papers, 2015 to 2016). A grade III or grade IV glioma arising from the central nervous system. "In this report, we show that the expression of ARHGDIA is frequently decreased in high-grade malignant gliomas." (PMID 26761212, 2016). "Here, we show that the expression of ARHGDIA is frequently decreased in high-grade malignant gliomas." (PMID 26761212, 2016). "We detected the endogenous expression level of ARHGDIA in three different malignant glioma cell lines, including H4, U251 and U87 cells." (PMID 27726098, 2016).
nephrotic syndrome (3 papers, 2015 to 2022). A collection of symptoms that include severe edema, proteinuria, and hypoalbuminemia; it is indicative of renal dysfunction. "Homozygous mutations in ARHGDIA have now been shown to cause nephrotic syndrome in several families, consistent with the animal studies." (PMID 26070612, 2015). "In line with findings in cases previously reported in the literature, our case presented with congenital nephrotic syndrome, confirming a crucial role of ARHGDIA for podocyte integrity." (PMID 36245711, 2022).
ovarian carcinoma (3 papers, 2015 to 2017). A malignant neoplasm originating from the surface ovarian epithelium. "For instance, ARHGDIA expression is upregulated in colorectal and ovarian cancers." (PMID 27726098, 2016).
pancreatic cancer (3 papers, 2015 to 2020). "ARHGDIA—a specific regulator of Rho protein exchange reactions crucial for JNK pathway—was previously identified by a bioinformatic pipeline that searched for candidate genes related to pancreatic cancer using protein-protein interactions and a shortest path approach." (PMID 32197468, 2020).
brain tumors (1 paper, 2016). "On the other hand, although ARHGDIA has been reported to decrease in brain tumors before, but there could not clearly clarify which member of RhoGDI family to change and its specific biological effects." (PMID 27726098, 2016).
Insulin resistance (1 paper, 2023). Increased resistance towards insulin, that is, diminished effectiveness of insulin in reducing blood glucose levels. "For example, the negatively associated protein ARHGDIA is a potent negative regulator of insulin sensitivity, and our fingerprint of insulin resistance contained its homologue ARHGDIB." (PMID 37494090, 2023).
meningioma (1 paper, 2022). A generally slow growing tumor attached to the dura mater. "When considering mitotic activity in meningiomas, we found negative correlations with DNAm for ARHGDIA and DOK7 and positive correlations for ESRRG and OTX1 (both correlating with all proliferation indices)." (PMID 36551712, 2022).
mental retardation (1 paper, 2012). "Furthermore, ARHGDIA preferentially impairs the forebrain functions required to form temporal associations, which is similar to mental retardation in humans." (PMID 23028951, 2012).
cancer (56 papers, 2008 to 2025). A tumor composed of atypical neoplastic, often pleomorphic cells that invade other tissues. "HeLa cell lysate was also used in the other western blots, with expression of ARHGEF1, ARHGEF11, ARHGEF12, ARHGAP5, ARHGAP24 and ARHGDIA protein reported in this cancer cell line." (PMID 18190708, 2008). "Secondly, it reduces Ubiquitin Specific Peptidase 4 (USP4) expression, leading to the degradation of ELAV Like RNA Binding Protein 1 (ELAVL1) protein and subsequently increasing Rho GDP Dissociation Inhibitor Alpha (ARHGDIA) levels, promoting cancer cell invasion and migration." (PMID 38711100, 2024). "The protein ARHGDIA has been found to play distinct roles in cancer progression for several tumors." (PMID 27726098, 2016). "Rho GDP dissociation inhibitor alpha (RhoGDIα) is frequently overexpressed in human tumours and chemoresistant cancer cell lines, raising the possibility that RhoGDIα is an anti-apoptotic molecule in cancer cells." (PMID 24130754, 2013). "TAGLN2 mRNA levels were significantly lower in cancer vs normal and ARHGDIA and YWHAZ levels elevated significantly and non-significantly, respectively, in the same data set." (PMID 31043708, 2019).
tumor (37 papers, 2002 to 2025). "miR-151-5p regulates tumor cell migration and spread; it is blocked by Rho GDP dissociation inhibitor alpha (Rho GDI alpha), and associated with the focal adhesion kinase gene." (PMID 30777008, 2019). "Silencing these targets, including tumour suppressors ARHGDIA and TAGLN2, phenocopied miR effects, demonstrating physiological relevance." (PMID 31043708, 2019). "Previous researches had indicated that downregulation of ARHGDIA had a different effect on the activation of Rho GTPase family members in different tumor types." (PMID 27726098, 2016). "In-silico analysis showed that several genes (CASZ1, IL1RAPL1, SOX17, N4BP1 and ARHGDIA) suggested to have tumor suppressive functions were target genes of miR-151." (PMID 22928040, 2012). "Knockdown of ARHGDIA, COBLL1, and TM4SF1 resulted in 2- to 4-fold increased levels of apoptosis in normal cells (ARHGDIA only) and tumor cells (all three genes)." (PMID 21569526, 2011). "ARHGDIA was the only gene in our RNAi studies found to impact apoptosis in both normal and tumor cells, with a generally greater magnitude of effect in tumor cells compared to the other 2 positive genes." (PMID 21569526, 2011). "Additionally, we found other abundant proteins in PDAC samples implicated in cytoskeletal dynamics, cell motility and tumor progression such as TUBB4A, SEPTIN7, ARHGDIA, THBS1, and PPP1R12A, similar to reports from the literature." (PMID 41007761, 2025). "Overexpression of ARHGDIA significantly inhibited tumor size and intracranial invasion." (PMID 26761212, 2016). "However, the regulatory mechanism of ARHGDIA suppression of tumor migration and invasion remains largely unexplored." (PMID 26761212, 2016). "However, depending on tumor type and stage, ARHGDIA can act as an oncosuppressor or oncogene." (PMID 37511924, 2023). "We provide evidence that ARHGDIA, COBLL1, and TM4SF1 are negative regulators of apoptosis in cultured tumor cells." (PMID 21569526, 2011). "ARHGDIA and TAGLN2 have both previously been shown to repress AR transcriptional activity, and to have tumour-suppressive roles; their downregulation has clear implications for PC development, and further supports oncogenic activity of miR-346, 361-3p and -197." (PMID 31043708, 2019). "We conducted a high-throughput RNA inhibition screen to knockdown gene expression levels of the four genes comprising the test (ARHGDIA, COBLL1, PKM2, TM4SF1) in both a human lung-derived normal and a tumor cell line using three different small inhibitory RNA molecules per gene." (PMID 21569526, 2011). "Knockdown of ARHGDIA, COBLL1, and TM4SF1 resulted in increased levels of apoptosis in normal cells (ARHGDIA only) and tumor cells (ARHGDIA, COBLL1, TM4SF1) relative to negative controls." (PMID 21569526, 2011).
ARHGDIA also shares sentences with these, for which no sentence is quoted: cardiac hypertrophy (4 papers); lung carcinoma (4); colon carcinoma (3); colorectal cancer (3); adenomyosis (2); breast tumor (2); cardiomyopathy (2); dilated cardiomyopathy (2); Hepatic fibrosis (2); HIV-1 infection (2); infection (2); lymphoma (2); melanoma (2); adrenocortical cancer (1); Alzheimer disease (1); anaplastic astrocytoma (1); asthma (1); astrocytoma (1); basophilic leukemia (1); behavioral disorders (1); benign tumors (1); brain cancer (1); carcinoma in-situ (1); cardiovascular disease (1); Cerebral ischemia (1); cervical cancer (1); co-infection (1); congestive heart failure (1); connective tissue disorder (1); COVID-19 (1).
A further 35 diseases each share a sentence with ARHGDIA in 1 paper.